SPHK1 (sphingosine kinase 1)
Diseases named in the same sentence as SPHK1 in open-access papers (continued):
Sharing a sentence is not in itself a finding about the gene and the disease.
lung carcinoma (23 papers, 2012 to 2025). "SPHK1 is also highly expressed in lung cancer and is closely associated with poor prognosis in LUAD patients and the malignant phenotype of NSCLC cells." (PMID 36823149, 2023). "Then, we focused on lung cancer patients to probe the relationship between SPHK1 expression and prognosis." (PMID 36823149, 2023). "To validate the function of SPHK1 in lung cancer, we established SPHK1 overexpression cell lines in A549 and 95D cells that low express SHPK1." (PMID 36823149, 2023). "The staining pattern of SphK1 was cytoplasmic as we previously reported in prostate and lung cancer." (PMID 35158767, 2022). "The accumulated data have indicated that SPHK1 is an integral component of the cancer cell network and can be “hijacked” for cell renewal and survival, including in breast, ovarian and lung cancer." (PMID 36361531, 2022). "SphK1 expression is higher at both the protein and the mRNA level; mRNA levels are nearly doubled in lung cancer tissue compared to normal tissue." (PMID 34690821, 2021). "Recent studies have demonstrated the possible potential molecular pathways for SPHK1 and HAS2 in cancer progression, one of which is that SPHK1 induces lung cancer cell migration and paclitaxel resistance by modulating IGF-1-induced EMT." (PMID 33506044, 2021). "Cell viability assay showed that enhanced SphK1 activity was involved in paclitaxel resistance of lung cancer cells." (PMID 31413745, 2019). "To clarify this issue, we examined the involvement of SphK1 in IGF-1-induced EMT using human lung cancer cell line A549, and its paclitaxel-resistant subline." (PMID 31413745, 2019). "This study demonstrates that DMS triggers the apoptosis of human lung cancer cells through the modulation of SPHK1, NF-κB and calcium signaling." (PMID 24173614, 2014). "Experimental research has shown that SPHK1 inhibitor can significantly improve the curative effects of chemotherapy drugs on lung cancer cells, as well as other types of cancer cells." (PMID 24173614, 2014). "A 2-fold increase of SphK1 mRNA expression and overwhelmingly positive immunostaining for SphK1, as compared to with patient-matched normal tissue, was observed in lung cancer tissues." (PMID 23028939, 2012). "In lung cancer (LC), they act as SphK1 inhibitors in NSCLC H1299 and A549 cell lines." (PMID 40964147, 2025). "By detecting the biological functions of SPHK1 overexpressed cell lines, we found that a high level of SPHK1 could promote proliferation, migration, and invasion capacity of lung cancer cells." (PMID 36823149, 2023). "Kaplan-Meier Plotter showed that lung cancer patients with high SPHK1 expression had a shorter OS." (PMID 36823149, 2023). "Therefore, we conclude that HOXC11 impacts the development of LUAD and facilitates lung cancer progression by promoting the expression of SPHK1." (PMID 36823149, 2023). "SphK1 and S1P have also been shown to have implications in lung cancer." (PMID 34690821, 2021). "In contrast, inhibition of SphK1 could attenuate lung cancer cell growth in vitro as well as in vivo." (PMID 26673009, 2016). "Compared to the SPHK2 inhibitor Opaganib, which only reduces the release of IL-6 from PBMC of lung cancer origin, inhibition of SPHK1 by PF543 can down-regulate both TNF-α and IL-6 release and more effectively inhibit lung cancer progression." (PMID 36823149, 2023). "In the present study, we demonstrated the abnormal signature of SPHK1 in NSCLC lesions and cell lines of lung cancers with a potential tumorigenic role in cell cycle regulation." (PMID 36361531, 2022). "Another study demonstrated that SphK1 elevated the expression of STAT3 and facilitated the progression of non−small-cell lung cancer." (PMID 35719962, 2022). "For instance, the circ-HIPK3 transcript acts as a microRNA-124 (miR-124) sponge and regulates the expression of miR-124 mRNA targets, including SphK1, CDK4, and STAT3, in lung cancer cells." (PMID 32692763, 2020).
lung carcinoma (continued). "In this study, we explored the role of SphK1 in IGF-1-induced EMT, migration and paclitaxel resistance of the human lung cancer cell line A549." (PMID 31413745, 2019). "Sphingosine kinase 1 (SPHK1), an enzyme that regulates synthesis of S1P, was found to be upregulated in different types of lung cancer and described as being involved in migration and tumor progression." (PMID 28938552, 2017). "Yu and colleagues elucidated that enriching circHIPK3 facilitated the expression of sphingosine kinase 1 (SphK1), cyclin-dependent kinase 4 (CDK4), and signal transducer and activator of transcription 3 (STAT3) through impeding miR-124 in lung cancer cells, and accelerating LC cell growth." (PMID 36292157, 2022). "SphK1/S1P signaling activates Hippo/YAP pathway and mtROS, and plays a significant role in pulmonary fibrosis, in which lungs become scarred over time and can lead to lung cancer." (PMID 33920887, 2021). "Similar findings were observed in VHL-positive CAKI-1 ccRCC and A549 lung cancer, suggesting that SphK1 activity regulates HIF-2α content regardless of the presence or absence of VHL." (PMID 26974204, 2016).
pulmonary fibrosis (23 papers, 2014 to 2025). Chronic progressive interstitial lung disorder characterized by the replacement of the lung tissue by connective tissue, leading to progressive dyspnea, respiratory failure, or right heart failure. "Genes that had higher upregulation in the single-virus infections were predominantly increased late (days 4 and/or 6) and included genes associated with inflammation (Angptl4) or pulmonary fibrosis (Fosl2, Pappa, and Sphk1)." (PMID 34160242, 2021). "Further studies are warranted determining the causal relationship between S1P/SPHK1 signaling and mtDNA release and repair in the pathobiology of lung fibrosis." (PMID 32764262, 2020). "SphK1-deficient mice were protected against bleomycin-induced pulmonary fibrosis, and the expression of SphK1 protein increased in the lung tissues of IPF patients compared with the control group." (PMID 30687087, 2018). "Furthermore, a murine model of bleomycin (BLM)-induced pulmonary fibrosis in Sphk1-deficient mice confirmed protection against PF, confirming the data from IPF patients depicting an enhanced SPHK1 and S1PL expression in lung tissues." (PMID 32192225, 2020). "In conclusion, this study identifies dysregulated sphingolipid metabolism, particularly SPHK1-S1p signaling, as a central mechanism driving fibrocyte recruitment and activation in pulmonary fibrosis." (PMID 40573254, 2025). "In conclusion, our study highlights the SPHK1 signaling axis as a key regulator of fibrocyte-mediated pulmonary fibrosis." (PMID 40573254, 2025). "To achieve this, we employed a bleomycin (BLM)-induced mouse model of lung fibrosis to investigate the molecular function of SPHK1 in pulmonary fibrosis." (PMID 40573254, 2025). "Our study indicates that SPHK1-S1p-S1PR1 signaling is a critical regulator of fibrocyte-mediated pulmonary fibrosis." (PMID 40573254, 2025). "The knockdown of SPHK1 increased survival and resistance to pulmonary fibrosis in bleomycin‐challenged mice." (PMID 37773702, 2023). "For example, silencing of sphingosine kinase 1 only in fibroblasts using fibroblast-specific protein 1-Cre mice model showed that fibroblast-specific gene inhibition is sufficient to mitigate pulmonary fibrosis induced by bleomycin." (PMID 35920332, 2022). "For instance, quercetin improves pulmonary fibrosis in mice models by inhibiting SphK1/S1P signaling." (PMID 33920887, 2021). "Quercetin alleviated pulmonary fibrosis by inhibiting sphingosine kinase 1 (SphK1)/S1P signaling, as demonstrated by in vivo and in vitro studies." (PMID 33995078, 2021). "Recent rodent studies show that lung tissue with bleomycin-induced pulmonary fibrosis has increased SphK1 expression and S1P levels." (PMID 34690821, 2021). "We reported increased sphingosine kinase 1 (SPHK1) in IPF lungs and that SPHK1 inhibition using genetic and pharmacologic approaches reduces murine bleomycin-induced pulmonary fibrosis." (PMID 32764262, 2020). "We reasoned that SPHK1 inhibition by PF543 administered following exposure to a fibrogenic agent will afford substantial protection against lung fibrosis by reducing AEC mtDNA damage and recruitment of Mo-AMs." (PMID 32764262, 2020). "We previously showed that concurrent treatment of mice with a nonspecific SPHK1 inhibitor, SK1-II, at the time of bleomycin exposure reduces lung fibrosis in a manner similar to that seen in the Sphk1-/- mice." (PMID 32764262, 2020). "S1P metabolic enzymes, especially SPHK1 and S1PL, are ubiquitously expressed in all cells and have crucial pathogenic roles in animal models of lung fibrosis and several human diseases, including IPF." (PMID 32764262, 2020). "Herein we address these two important gaps in our understanding of the SPHK1/S1P axis by showing that PF543, a specific SPHK1 inhibitor, administered following exposure to either bleomycin or asbestos, mitigates murine pulmonary fibrosis." (PMID 32764262, 2020).
pulmonary fibrosis (continued). "Collectively, these studies firmly support that SPHK1 inhibition with PF543 begun following exposure to two different fibrogenic agents can mitigate pulmonary fibrosis." (PMID 32764262, 2020). "A major finding in this study is that SPHK1 inhibition initiated following exposure to two different fibrogenic agents significantly reduced pulmonary fibrosis." (PMID 32764262, 2020). "A previous study showed that the level of S1P regulated by TGF-β is also affected by the expression of SphK1 in lung fibrosis." (PMID 30687087, 2018). "In lung pathologies such as asthma, pulmonary fibrosis and pulmonary hypertension, genetic deletion of Sphk1 or inhibition of SphK1 activity with small molecule inhibitors conferred significant protection from airway/lung inflammation and injury." (PMID 28851267, 2017). "SPHK1 is a key enzyme in the sphingolipid metabolic pathway and has been widely studied in the context of cancer, cardiovascular disease, and organ fibrosis, including liver and pulmonary fibrosis." (PMID 41333463, 2025). "Dysregulation of the SPHK1-S1p-S1PR1 axis has been linked to pathological inflammation and tissue remodeling, but its role in fibrocyte-mediated pulmonary fibrosis remains unclear." (PMID 40573254, 2025). "In this study, we sought to identify key therapeutic targets within the sphingolipid metabolism pathway that contribute to the pathogenesis of lung fibrosis and to elucidate how these targets, particularly SPHK1, influence the fibrotic process through their effects on fibrocytes." (PMID 40573254, 2025). "Additionally, SPHK1 inhibition has been shown to alleviate pulmonary fibrosis and enhance survival in animal models." (PMID 40573254, 2025). "We determined whether PF543, a specific SPHK1 inhibitor post bleomycin or asbestos challenge mitigates lung fibrosis by reducing mitochondrial (mt) DNA damage and pro-fibrotic monocyte recruitment—both are implicated in the pathobiology of pulmonary fibrosis." (PMID 32764262, 2020). "Although beyond the scope of this study, it will be of interest determining whether conditional SPHK1 knockdown in macrophages is sufficient for mitigating pulmonary fibrosis." (PMID 32764262, 2020). "Additionally, a role for SPHK1 was also shown using two alternative models, namely the radiation-induced lung injury/pulmonary fibrosis (RILI/PF) and asbestos-induced lung fibrosis (AIPF) models." (PMID 32549377, 2020). "Thus, SPHK1 appears to be a viable target to ameliorate the development of lung fibrosis in preclinical models; however, clinical trials to determine the efficacy of SPHK1 inhibitor(s) in treating IPF are required." (PMID 32549377, 2020). "Using cell-targeted conditional SPHK1 knockout mice, we recently reported the specific role of SPHK1 in AECs and fibroblasts, but not endothelial cells, in the development of bleomycin-induced lung fibrosis." (PMID 32764262, 2020). "Moreover, activated SphK1 mediates the enhanced mtROS production and expression of fibronectin and α-smooth muscle actin, leading to fibroblast activation, which has a driving role in pulmonary fibrosis." (PMID 33920887, 2021). "To determine whether post-exposure to PF543, a SPHK1 specific inhibitor can reduce lung fibrosis in vivo, we used two murine pulmonary fibrosis models resulting from exposure to either bleomycin (spontaneously resolves) or amphibole crocidolite asbestos (nonresolving)." (PMID 32764262, 2020). "In addition, results provided direct evidence that SphK1 may become a new type of target for treating pulmonary fibrosis." (PMID 30687087, 2018). "We have also shown a role for SPHK1/S1P signaling in TGF-β-induced YAP1 activation and mitochondrial ROS generation, resulting in fibroblast activation, a critical driver of pulmonary fibrosis." (PMID 36498853, 2022). "SphK1 deletion and S1PR2 deletion in lung fibroblasts have both been shown to be protective against bleomycin-induced pulmonary fibrosis in mice." (PMID 34690821, 2021).
pulmonary fibrosis (continued). "Here, we provide evidence that the SPHK1/S1P signaling pathway in the alveolar epithelial cells and fibroblasts—but not in endothelial cells—is pro-fibrotic in a BLM mouse model of pulmonary fibrosis." (PMID 32192225, 2020). "Taken together, these findings suggest that the SPHK1 signaling axis is an innovative therapeutic target for managing patients with IPF and other forms of lung fibrosis by ameliorating AEC mtDNA damage and Mo-AM recruitment." (PMID 32764262, 2020). "However, it is unknown whether administration of SPHK1 specific inhibitor PF543, following exposure to fibrogenic agents can still mitigate pulmonary fibrosis and, if so, whether the SPHK1/S1P pathway impacts AEC mtDNA integrity and recruitment of pro-fibrotic Mo-AMs." (PMID 32764262, 2020). "Recent studies from our laboratory and others have provided strong evidence for the SPHK1/S1P signaling axis in the pathogenesis of IPF and experimental lung fibrosis." (PMID 32192225, 2020). "Blocking SPHK1 with SKI-II attenuated lung inflammation and development of lung fibrosis 3 weeks post-bleomycin challenge indicating a long-term beneficial effect of this SPHK1 inhibitor." (PMID 32549377, 2020). "Further studies are essential to determine potential interactions between SPHK1/S1P/YAP1 and NOX4 in the modulation of TGF-β mediated mtROS and pulmonary fibrosis." (PMID 32192225, 2020). "Collectively, these data suggest that AEC mtDNA damage promotes apoptosis and lung fibrosis; however, the relationship between AEC mtDNA damage and S1P/SPHK1 signaling in the pathobiology of lung fibrosis is unclear." (PMID 32764262, 2020). "Taken together, our new findings suggest that SPHK1 inhibition can reduce lung and AEC mtDNA damage that promotes lung fibrosis." (PMID 32764262, 2020). "SphK1 knockout or inhibiting SphK activity can reduce the expression of S1P and the secretion of TGF-β in cells, which can also reduce bleomycin-induced mouse pulmonary fibrosis." (PMID 30687087, 2018). "Moreover, the pharmacological inhibition of SPHK1 or the functional antagonism of S1PR1 disrupted fibrocyte trafficking, reduced extracellular matrix deposition, and ameliorated lung fibrosis, underscoring the therapeutic potential of targeting this pathway." (PMID 40573254, 2025). "To determine whether blocking SPHK1-derived S1p signaling could mitigate fibrocyte activity and reduce lung fibrosis, we used SKI-349, a selective SPHK1 inhibitor, in the BLM model." (PMID 40573254, 2025). "We reason that SPHK1 signaling may be an innovative therapeutic target for managing patients with IPF and other forms of lung fibrosis." (PMID 32764262, 2020). "Interestingly, the partial deletion of Sgpl1 (Sgpl1+/−) in mice accentuated BLM-induced pulmonary fibrosis in mice, suggesting a balance between TGF-β-mediated SPHK1 and S1P lyase expression in regulating S1P levels and fibrogenesis." (PMID 32192225, 2020). "A second mechanistic pathway that we explored was whether SPHK1 inhibition can reduce mtDNA damage in the lungs and AEC, which is crucial for promoting AEC mitochondria-regulated apoptosis and pulmonary fibrosis." (PMID 32764262, 2020). "Genetic deletion of Sphk1 in fibroblasts and AECs, but not endothelial cells, protected mice from bleomycin-induced lung fibrosis." (PMID 32549377, 2020). "More recently, we reported that bleomycin-induced pulmonary fibrosis is reduced by a nonspecific SPHK inhibitor (SKI-II) or conditional deletion of Sphk1 in murine AEC or fibroblasts, but not in endothelial cells." (PMID 32764262, 2020). "The increased S1PL expression in LPS- and VILI-induced mouse lungs correlated with decreased S1P levels; however, in pulmonary fibrosis both SphK1 and S1PL expressions were elevated and blocking S1PL accentuated bleomycin-induced pulmonary fibrosis suggested a protective role of S1PL in fibrosis." (PMID 29301259, 2018).
pulmonary fibrosis (continued). "Given the importance of sphingosine kinase 1 (SPHK1) in promoting pulmonary fibrosis, we recently reported the first asbestos post-exposure study demonstrating that PF543, a specific SPHK1 inhibitor, can attenuate lung fibrosis when initiated 1 month following asbestos exposure." (PMID 34202229, 2021). "Furthermore, bleomycin-induced pulmonary fibrosis is mitigated by a global SPHK inhibitor or genetic deletion of Sphk1-/-, but not Sphk2-/- in mice." (PMID 32764262, 2020). "Therefore, in addition to fibroblasts, the knockdown of Sphk1 in macrophages and epithelial cells may also contribute to BLM-induced pulmonary fibrosis." (PMID 32192225, 2020). "In the murine model of lung fibrosis, bleomycin-induced TGF-β secretion and phosphorylation of SMAD2/3, AKT, JNK1, and p38 MAPK were mitigated in Sphk1 deleted or SPHK1 inhibitor administered mice, demonstrating the interaction between the TGF-β and SPHK1/S1P signaling axis in vivo." (PMID 32549377, 2020). "However, the role of SPHK1 in FN, α-SMA expression, and mtROS production in lung fibrosis is unknown." (PMID 32192225, 2020). "Knockdown of SphK1 in mice conferred protection against hypoxia-induced pulmonary artery hypertension, hyperoxia-induced lung injury in neonatal bronchopulmonary dysplasia and bleomycin-induced pulmonary fibrosis but not in VILI as demonstrated here." (PMID 29301259, 2018). "Here, we show that the conditional deletion of Sphk1 in AECs and fibroblasts (but not in endothelial cells) protected the mice from BLM-induced lung fibrosis." (PMID 32192225, 2020). "In preclinical models of pulmonary fibrosis and pulmonary artery hypertension (PAH), genetic deletion of Sphk1 or inhibition of SPHK1 (but not SPHK2) activity with PF543, a small molecule inhibitor of SPHK1, reduced bleomycin-induced development of lung fibrosis or hypoxia-induced PAH in mice." (PMID 35163176, 2022).